RN7SL408P (RNA, 7SL, cytoplasmic 408, pseudogene)
Gene: Miscellaneous RNA gene on chromosome 6 (134,133,573 to 134,133,868, forward strand). Ensembl gene ENSG00000266875.
Homologues: Orthologues: chimpanzee Metazoa_SRP (99% identical), macaque Metazoa_SRP (91% identical). Paralogues in human: RN7SL2 (88% identical), RN7SL1 (88% identical), RN7SL3 (87% identical), RN7SL664P (83% identical), RN7SL88P (83% identical), RN7SL15P (83% identical), RN7SL296P (83% identical), RN7SL44P (83% identical), RN7SL448P (82% identical), RN7SL47P (82% identical), RN7SL823P (82% identical), RN7SL126P (82% identical), and 705 more.